LRTM3 (leucine rich repeat transmembrane protein 3)
Synonyms: C13orf40; CCDC168; FLJ40176
Tractability: Antibody: UniProt predicts a signal peptide or a membrane-spanning region; the Human Protein Atlas places it where antibodies can reach. PROTAC: ubiquitination databases record sites on it.
Gene: Protein-coding gene on chromosome 13 (102,729,367 to 102,759,072, reverse strand). Ensembl gene ENSG00000175820.
Subcellular location: Membrane
Subcellular location (Human Protein Atlas): Plasma membrane
Gene Ontology:
Cellular component: membrane
Genetic constraint (gnomAD): Loss-of-function variants: 5 observed, 5.98 expected, observed/expected ratio (o/e) 0.84, 90% interval 0.43 to 1.66. That is too few expected variants to judge how well the gene tolerates losing a copy. Missense variants: 7,836 observed, 8,441.9 expected, observed/expected ratio (o/e) 0.93, 90% interval 0.91 to 0.95. Synonymous variants: 2,718 observed, 2,928.2 expected, observed/expected ratio (o/e) 0.93, 90% interval 0.9 to 0.96.
Homologues: Orthologues: mouse Ccdc168 (32% identical).
Diseases named in the same sentence as LRTM3 in open-access papers:
LRTM3 is named in the same sentence as 14 diseases in open-access papers, as found by Europe PMC text mining. Sharing a sentence is not in itself a finding about the gene and the disease.
LRTM3 shares sentences with these, for which no sentence is quoted: tumor (3 papers); cancer (2); colon adenocarcinoma (2); colorectal cancer (2); renal cell carcinoma (2); adenosquamous carcinoma of the prostate (1); infection (1); kidney cancer (1); malignant pleural mesothelioma (1); ovarian carcinoma (1); prostate carcinoma (1); stomach adenocarcinomas (1); thymoma (1); uterine body mixed cancer (1).